DCAF15 (DDB1 and CUL4 associated factor 15)
Description:
Substrate-recognition component of the DCX(DCAF15) complex, a cullin-4-RING E3 ubiquitin-protein ligase complex that mediates ubiquitination and degradation of target proteins. The DCX(DCAF15) complex acts as a regulator of the natural killer (NK) cells effector functions, possibly by mediating ubiquitination and degradation of cohesin subunits SMC1A and SMC3. May play a role in the activation of antigen-presenting cells (APC) and their interaction with NK cells. Binding of aryl sulfonamide anticancer drugs, such as indisulam (E7070) or E7820, change the substrate specificity of the DCX(DCAF15) complex, leading to promote ubiquitination and degradation of splicing factor RBM39. RBM39 degradation results in splicing defects and death in cancer cell lines. Aryl sulfonamide anticancer drugs change the substrate specificity of DCAF15 by acting as a molecular glue that promotes binding between DCAF15 and weak affinity interactor RBM39. Aryl sulfonamide anticancer drugs also promote ubiquitination and degradation of RBM23 and PRPF39.
Synonyms: C19orf72; MGC99481
Tractability: Small molecule: a structure with a bound ligand is known. PROTAC: ubiquitination databases record sites on it.
Gene: Protein-coding gene on chromosome 19 (13,952,459 to 13,961,449, forward strand). Ensembl gene ENSG00000132017.
Subcellular location (Human Protein Atlas): Mitochondria; Vesicles
Gene Ontology:
Molecular function: protein binding; small molecule binding
Biological process: protein polyubiquitination; regulation of natural killer cell activation; protein ubiquitination
Cellular component: Cul4-RING E3 ubiquitin ligase complex; Cul4A-RING E3 ubiquitin ligase complex; Cul4B-RING E3 ubiquitin ligase complex
Genetic constraint (gnomAD): Loss-of-function variants: 24 observed, 67.3 expected, observed/expected ratio (o/e) 0.36, 90% interval 0.26 to 0.5. The upper end of that interval is the gene's LOEUF score, 0.5, which puts it in group 2 of 6, group 1 being the genes least tolerant of losing a copy. Missense variants: 627 observed, 822.46 expected, observed/expected ratio (o/e) 0.76, 90% interval 0.71 to 0.81. Synonymous variants: 376 observed, 336.2 expected, observed/expected ratio (o/e) 1.12, 90% interval 1.03 to 1.22.
Homologues: Orthologues: chimpanzee DCAF15 (99% identical), macaque DCAF15 (99% identical), dog DCAF15 (94% identical), pig DCAF15 (94% identical), mouse Dcaf15 (91% identical), rat Dcaf15 (91% identical), guinea pig DCAF15 (84% identical), tropical clawed frog dcaf15 (66% identical), zebrafish dcaf15 (58% identical), Drosophila melanogaster CG6325 (24% identical).
Diseases named in the same sentence as DCAF15 in open-access papers:
DCAF15 is named in the same sentence as 19 diseases in open-access papers, as found by Europe PMC text mining. Sharing a sentence is not in itself a finding about the gene and the disease. The quoted sentences say what the papers report.
acute myeloid leukemia (4 papers, 2022 to 2024). Acute myeloid leukemia (AML) is a group of neoplasms arising from precursor cells committed to the myeloid cell-line differentiation. "Using a domain-focused genetic screening approach, we reveal DCAF15 as an acute myeloid leukemia (AML)-biased dependency." (PMID 38961054, 2024). "Here, the authors reveal DCAF15 as a cell autonomous acute myeloid leukemia dependency sustaining proliferation through control of cohesin complex recycling dynamics." (PMID 38961054, 2024). "For instance, DCAF15 is upregulated in some acute myeloid leukemia (AML) patients with respect to normal hematopoietic progenitors and AML cells which showed strong dependency on RBM39 expression." (PMID 35406598, 2022). "Interestingly, RBM39 degradation was described as a biomarker of indisulam response in acute myeloid leukemia and DCAF15 levels were shown to correlate with indisulam response in hematopoietic and lymphoid cancers." (PMID 35534224, 2022). "Interestingly, DCAF15 is found to be more highly expressed in Acute Myeloid Leukemia (AML) patient samples compared to normal hematopoietic progenitors." (PMID 38571491, 2024).
leukemia (4 papers, 2019 to 2024). A malignant (clonal) hematologic disorder, involving hematopoietic stem cells and characterized by the presence of primitive or atypical myeloid or lymphoid cells in the bone marrow and the blood. "Several reports have also shown that neuroblastoma, leukemia, myeloma, and lymphoma are sensitive to indisulam due to their high expression of DCAF15." (PMID 39004623, 2024). "This outcome is consistent with the previous study, which showed DCAF15 in leukemia cells as a negative regulator of NK function." (PMID 37348499, 2023). "Inhibiting DCAF15 with a drug also made natural killer cells more efficient at eliminating leukemia cells." (PMID 31452512, 2019). "Patients with leukemia whose cancer cells make little DCAF15 protein have a better chance of survival, suggesting that this process may already be happening in some patients." (PMID 31452512, 2019). "Together these data indicate that targeting DCAF15 in leukemia patients may help natural killer cells attack cancer cells." (PMID 31452512, 2019). "Additionally, DCAF15 is up-regulated in AML patients compared to normal hematopoietic cells, suggesting that leukemia cells may hijack normal DCAF15 function during oncogenesis." (PMID 38961054, 2024).
neuroblastoma (4 papers, 2021 to 2025). Neuroblastoma (NB) is the most common solid, extracranial childhood tumor. "Here, we show that the RBM39 dependence and high levels of DCAF15 expression in neuroblastoma account for exceptional efficacy and a high therapeutic index of indisulam in a variety of high-risk neuroblastoma models." (PMID 34788094, 2021). "However, several studies have demonstrated that cancers derived from hematopoietic and lymphoid lineages, or high-risk neuroblastomas, are sensitive to indisulam because of their high expression levels of DCAF15, by targeting RNA splicing." (PMID 39004623, 2024). "To study the essentiality of DCAF15 in the mode of action of aryl sulfonamides in neuroblastoma, we generated DCAF15 knockout cells using CRISPR–Cas9 in KELLY in which loss of DCAF15 rescued acute RBM39 degradation from indisulam treatment (6 h, 10 μM)." (PMID 35296644, 2022). "In neuroblastoma models, indisulam induces rapid loss of RBM39, accumulation of splicing errors and growth inhibition in a DCAF15-dependent manner." (PMID 35296644, 2022). "Together, these data demonstrate that DCAF15 expression levels determine the efficacy of indisulam with high levels of DCAF15 in neuroblastoma conferring more sensitivity to indisulam treatment." (PMID 34788094, 2021). "We further compared DCAF15 expression between neuroblastomas and other types of pediatric cancers, among 2222 cases analyzed by RNA-seq (St." (PMID 34788094, 2021). "Among cell lines representing 26 different cancer lineages, neuroblastoma cells expressed relatively high levels of DCAF15 mRNA, comparable to blood and lymphoma lineages." (PMID 34788094, 2021). "Mechanistically, the dependency on RBM39 and high-level expression of DCAF15 determine the exquisite sensitivity of neuroblastoma to indisulam." (PMID 34788094, 2021). "Jude Cloud), and found that neuroblastoma had the second highest levels of DCAF15, behind only retinoblastoma." (PMID 34788094, 2021). "To directly test whether the antiproliferative effect of indisulam in neuroblastoma cells depends on DCAF15 expression, we engineered neuroblastoma cell lines to either overexpress DCAF15, silence DCAF15, or rescue DCAF15 in DCAF15 knockout (KO) cells." (PMID 34788094, 2021). "Although neuroblastoma expresses high levels of DCAF15 and is highly responsive to indisulam in comparison with other cancer lineages, it might be necessary in the future to stratify patients who are most likely to have the best response." (PMID 34788094, 2021). "Relatively high DCAF15 expression may, in part, explain the exquisite sensitivity of neuroblastoma cancers to indisulam." (PMID 34788094, 2021). "Here, we demonstrate that neuroblastoma is both dependent on RBM39 and expresses relatively high levels of DCAF15, providing a mechanistic rationale for indisulam treatment." (PMID 34788094, 2021). "After establishing the dependency of neuroblastoma on RBM39, we investigated what role DCAF15 expression levels play in determining the high activity of indisulam in neuroblastoma over other cancer lineages." (PMID 34788094, 2021). "The high levels of DCAF15 and RBM39 dependence in neuroblastoma might make indisulam especially efficacious against this MYC-driven cancer." (PMID 34788094, 2021). "Thus, it was confirmed that DCAF15 is necessary for the mechanism of action of two RBM39-degraders indisulam and E7820 in neuroblastoma including downstream consequences such as RNA mis-splicing and perturbations to key factors in cell cycle progression and metabolism." (PMID 35296644, 2022).
gastric cancer (2 papers, 2023 to 2025). A primary or metastatic malignant neoplasm involving the stomach. "It has been reported that ubiquitin E3 ligase DCAF15 mediates the sensitivity of gastric cancer cells to Indisulam." (PMID 40465651, 2025). "Taken together, we discovered a new substrate ZEB1 for DCAF15 induced by the molecule glue indisulam and elucidated the molecular mechanism by which indisulam regulates the migration of gastric cancer cells." (PMID 36805336, 2023). "Collectively, these data demonstrated that indisulam inhibited the migration of gastric cancer cells by degrading ZEB1 through DCAF15." (PMID 36805336, 2023). "Without indisulam, DCAF15 could significantly downregulate ZEB1 in HCC cells while DCAF15 could hardly regulate ZEB1 in gastric cancer cells." (PMID 36805336, 2023). "Since DCAF15 is required for the inhibitory effect of indisulam on the migration of gastric cancer cells, we thought that DCAF15-interacting proteins may participate in this regulation." (PMID 36805336, 2023). "Since our cell line–based experiments discovered that indisulam directly modulated ZEB1, we analyzed the expression level of ZEB1 instead of N-cadherin and DCAF15 in gastric cancer tissues to further explore the role of ZEB1 in the progression of gastric cancer." (PMID 36805336, 2023). "Therefore, we thought to test whether DCAF15 is also required for the inhibitory effect of indisulam on the migration of gastric cancer cells." (PMID 36805336, 2023). "However, indisulam enhances the interaction between DCAF15 and ZEB1 and thus significantly enhanced the ubiquitination and subsequent degradation of ZEB1 in gastric cancer cells." (PMID 36805336, 2023). "Our previous experiments revealed that alteration of DCAF15 expression did not affect the proliferation of gastric cancer cells in the absence of indisulam." (PMID 36805336, 2023). "However, after ZEB1 knockdown, further knockdown of DCAF15 did not alter the effect of indisulam on the migration of gastric cancer cells." (PMID 36805336, 2023). "Similarly, our current experiments showed that neither overexpression nor knockdown of DCAF15 altered the ZEB1 protein level or inhibited the migration of gastric cancer cells." (PMID 36805336, 2023).
hepatocellular carcinoma (2 papers, 2021 to 2023). A malignant tumor that arises from hepatocytes. "Thus, DCAF15 promotes the ubiquitination and degradation of ZEB1 and negatively regulates its protein level, thereby suppressing malignancy of hepatocellular carcinoma (HCC)." (PMID 36805336, 2023).
lung adenocarcinoma (2 papers, 2024 to 2026). A carcinoma that arises from the lung and is characterized by the presence of malignant glandular epithelial cells. "Alterations encompassing DCAFs are frequently observed in lung adenocarcinoma, and DCAF15 has been shown to be frequently lost." (PMID 39251997, 2024). "Analysis of The Cancer Genome Atlas (TCGA) data revealed that seven DCAF genes (DCAF2, DCAF4, DCAF7, DCAF12, DCAF13, DCAF15, and DCAF17) were significantly upregulated in lung adenocarcinoma (LUAD)." (PMID 41047465, 2026).
B-cell lymphoma (1 paper, 2019). "We repeated NK-92 competitive co-culture experiments after disruption of DCAF15, PTPN2, STAT1 and ICAM1 in Daudi cells, a B2M-deficient B-cell lymphoma line." (PMID 31452512, 2019).
chronic myeloid leukemia (1 paper, 2024). "Additionally, a CRISPR screen performed in chronic myeloid leukemia (CML) cells demonstrated that DCAF15 is a negative regulator of natural killer (NK) cell-mediated clearance of cancer cells." (PMID 38961054, 2024).
myeloid malignancies (1 paper, 2019). "Given the in vitro findings, we hypothesized that lower DCAF15 expression in myeloid malignancies could be associated with better clinical outcomes." (PMID 31452512, 2019). "While these clinical data are preliminary in nature, they provide a rationale for drugging DCAF15 in myeloid neoplasms, achieved through judicious dosing of existing anti-cancer sulfonamides or the development of pure DCAF15 inhibitors." (PMID 31452512, 2019).
ovarian carcinoma (1 paper, 2023). A malignant neoplasm originating from the surface ovarian epithelium. "One of the candidate TICTOC genes, DCAF15, was found frequently amplified in ovarian cancer, and DCAF15 inhibition led to enhanced NK cell-mediated cytotoxicity, suggesting CNAs as alternative immunotherapy targets in ovarian cancers that are resistant to traditional ICI." (PMID 37348499, 2023).
cancer (13 papers, 2019 to 2025). A tumor composed of atypical neoplastic, often pleomorphic cells that invade other tissues. "Indisulam was previously identified as an aryl sulfonamide anti-cancer drug to dysregulate DCAF15 binding partners and showed strong specificity to DCAF15 and similar functional effect compared with DCAF15 knockout." (PMID 37348499, 2023). "Pharmacologic depletion of RNA-binding motif 39 (RBM39) using aryl sulfonamides represents a promising anti-cancer therapy but requires high levels of the adaptor protein DCAF15." (PMID 37666821, 2023). "Disruption of DCAF15 strongly sensitized cancer cells to NK-mediated killing, resulting from increased cancer cell expression of lymphocyte costimulatory molecules." (PMID 31452512, 2019). "We discovered and characterized how disruption of DCAF15 or PTPN2 sensitizes a variety of cancer cell types to both NK-92 and primary NK cells." (PMID 31452512, 2019). "The main experiment, in which every single protein in the cancer cells was deleted one by one, revealed that a protein called DCAF15 changes how cancer and natural killer cells interact." (PMID 31452512, 2019). "Surprisingly, disrupting the ubiquitin ligase substrate adaptor DCAF15 strongly sensitized cancer cells to NK-mediated clearance." (PMID 31452512, 2019). "In addition, in most cancer types, except for CHIP and DCAF15, other ligases are highly associated with GSPT1." (PMID 41194439, 2025). "Accordingly, the control of RBM39 homoeostasis is important for cancer cell survival, and therefore the identification of alternative approaches to lower the intracellular concentration of RBM39 independently of DCAF15 could be beneficial for cancer treatment." (PMID 37666821, 2023). "By pushing the splicing equilibrium towards the constitutive inclusion of the poison exon, the expression of RBM39 could be shut down, resulting in cancer cell death in a DCAF15-independent manner." (PMID 37666821, 2023). "In addition, we report the potential role of DCAF15 in modulating TLS functions; notably, only interactions between NK cells and cancer cells, based on pharmacological inhibition of DCAF15, are investigated." (PMID 37348499, 2023). "Interestingly, analysis of the Broad Institute Cancer Dependency Map (DepMap) revealed that DCAF15 and the histone deacetylase HDAC8 are top cancer co-dependencies, suggesting that these proteins may function together in the same cohesin recycling process." (PMID 38961054, 2024). "Mechanistically, DCAF15 inhibition was associated with upregulated expression of the co-stimulatory molecule CD8054; DCAF15 inhibition was also shown to disrupt alternative splicing in cancer cells and generates neoantigens, which stimulate T cell-mediated clearance." (PMID 37348499, 2023). "KRAS4A splicing is controlled by the DCAF15/RBM39 pathway, and deletion of KRAS4A or pharmacological inhibition of RBM39 using Indisulam leads to inhibition of cancer stem cells." (PMID 34257283, 2021). "Previous studies have reported that immunomodulatory drugs, such as sulfonamides, can recruit the splicing factor RBM39 to the E3 ligase substrate receptor DCAF15, leading to ubiquitination and degradation of RBM39, which resulted in altered RNA splicing and death in some cancer cell lines." (PMID 35989423, 2022). "Consistent with this hypothesis, among 709 different cancer cells in the CTRP, we found a significant correlation between indisulam sensitivity and DCAF15 expression." (PMID 34788094, 2021). "Leukemia cells lacking DCAF15 could be attacked by natural killer cells much more easily because the cancer cells exhibited inflammation-like symptoms that stimulated the immune response." (PMID 31452512, 2019). "Therefore, DCAF15 expression alone may not be sufficient to stratify cancer patients for E7820 treatment." (PMID 38789724, 2024).
tumor (7 papers, 2021 to 2026). "Inhibition of DCAF15 was found to dysregulate the splicing pathway and enhance NK- and T cell-mediated anti-tumor immunity." (PMID 37348499, 2023). "The efficacy of indisulam in reducing tumor growth in xenograft studies was higher in cells ectopically expressing DCAF15 and lower in DCAF15-silenced cells." (PMID 34788094, 2021). "We therefore selected DCAF15 to validate its function to alter anti-tumor immunity." (PMID 37348499, 2023). "Although DCAF15 is a strong determinant for indisulam sensitivity as shown by us and others, a recent study suggested that DCAF15 mRNA levels in primary samples of tumour cells of AML patients did not correlate to RBM39 degradation." (PMID 35296644, 2022). "After knocking out DCAF15, tumor cells become resistant to indisulam, and even 5 μM indisulam cannot degrade RBM39, nor does it induce apoptosis in T-ALL tumor cells." (PMID 39044280, 2024).
hematological cancer (1 paper, 2019). "Dose-response experiments across a panel of 16 hematological cancer cell lines confirmed the reported positive relationship between DCAF15 mRNA expression levels and indisulam sensitivity (R2 = 0.33, p=0.02)." (PMID 31452512, 2019).
infection (1 paper, 2024). The state of being infected such as from the introduction of a foreign agent such as serum, vaccine, antigenic substance or organism. "MV4-11 cells were transduced with an sgRNA targeting DCAF15 and sorted/collected 4 days after infection." (PMID 38961054, 2024).
DCAF15 also shares sentences with these, for which no sentence is quoted: lymphoma (3 papers); glioblastoma (1); lentivirus infection (1); myeloma (1); retinoblastoma (1).